SSTR2 (somatostatin receptor 2)
Diseases named in the same sentence as SSTR2 in open-access papers (continued):
Sharing a sentence is not in itself a finding about the gene and the disease.
cancer (continued). "While SSTR2 has traditionally been viewed as an inhibitory receptor involved in suppressing hormone secretion and cell proliferation, emerging evidence suggests a more complex role in cancer biology." (PMID 41002582, 2025). "Therefore, NODAGA-cLAB4-TATE has the potential to advance clinical use of radiocopper in SSTR2 targeted cancer theranostics." (PMID 39310112, 2024). "This shift may result from radiation-induced upregulation of SSTR2 expression observed in different cancer models, resulting in a higher uptake of radiolabeled somatostatin analogues." (PMID 39324010, 2024). "The review concludes by underscoring the significant potential of TAT in treating SSTR2-overexpressing cancers, especially in patients refractory to β-PRRT, while also acknowledging the current challenges and the necessity for further research to optimize treatment protocols." (PMID 38543120, 2024). "We found that SSTR2 tends to be positively correlated with immune signature scores in most cancers." (PMID 35264912, 2022). "Our results suggest that SSTR2 expression varies among the types of cancer and patients with high SSTR2 expression could obtain longer OS after ICIs treatment." (PMID 35264912, 2022). "We found the SSTR2 IHC-positive rate of 13 cancers to be above 50%." (PMID 35264912, 2022). "Our findings suggest that SSTR2-high groups may have better immune cell infiltration than SSTR2-low groups in various cancers." (PMID 35264912, 2022). "Additionally, SSTR2-high groups of most cancers had higher median central memory CD4 T cell scores, activated CD4 T cell scores, and effector memory CD4 T cell scores (96.15%, 80.77%, and 88.46%, respectively)." (PMID 35264912, 2022). "In the HPA, we found the SSTR2 IHC-positive rate of 13 cancers to be above 50%." (PMID 35264912, 2022). "Notably, octreotide-functionalized NDS showed enhanced toxicity toward SSTR2-positive cancer cells through endocytosis." (PMID 34575511, 2021). "However, SSTR2 mRNA levels are still relatively high compared to cell lines derived from other types of cancer." (PMID 33085037, 2021). "Also, SSTR2, which is reported to have an anti-proliferative effect in cancer cells, is a downstream target of HIVEP223." (PMID 33420027, 2021). "Thus, epigenetic drug-induced upregulation of SSTR2 has the potential for becoming additional therapeutic option for improving PRRT of NET cancers." (PMID 33435224, 2021). "We next evaluated whether the increased SSTR2 levels induced by the miR-16-5p mimic affected the anti-cancer properties of octreotide." (PMID 33045023, 2020). "Recent data suggest that methylation may be a relevant mechanism for controlling SSTR2 expression in cancer." (PMID 25010045, 2014). "Furthermore, a clinical use of PEN-221 to eliminate CAR T cells may differ from the dose–response determined from the ongoing trials against SSTR2 positive cancer patients (NCT02936323)." (PMID 36463361, 2022). "However, the wide expression of SSTR2 argues against antagonism for this receptor for future pharmacological development, as this may influence many systems; importantly, the Sstr2 has been found to be highly expressed in certain types of cancers." (PMID 33434183, 2021). "Although SSTR2 is significantly expressed in HCC, its relationship with the clinicopathological features of this cancer remains poorly characterized." (PMID 41002582, 2025). "The evolving landscape of RPT prominently centers on two clinically approved cancer targets: prostate-specific membrane antigen (PSMA) and somatostatin receptor 2 (SSTR2)." (PMID 39629134, 2024). "In our study, we identified six signature genes, namely TNFRSF11B, METTL7B, SSTR2, OXTR, CDKN2C, and H19 which have been extensively studied in the past and are known to play a significant role in cancer." (PMID 37713112, 2024).
cancer (continued). "As outlined in Section 3, it is evident that the epigenetic regulation of PNETs remains an insufficiently explored domain in comparison to other extensively researched cancers, barring a few exceptions like the MEN1 and SSTR2 signaling pathways." (PMID 38279330, 2024). "The cancer cells express synaptophysin (SYP), chromogranin A (CgA), somatostatin receptor 2 (SSTR2) and gastrin (often focal)." (PMID 36830839, 2023). "Somatostatin receptor 2 (SSTR2), the most abundant receptor of somatostatin (SST), possesses immunoreactivity and is altered in many cancers." (PMID 35264912, 2022). "Cluster 1 has the maximum score 32.549, with 52 nodes and 830 edges, including known cancer-related genes, such as ANXA1 (annexin A1) and SSTR2 (somatostatin receptor type 2)." (PMID 34512870, 2021). "Somatostatin receptor 2 (SSTR2) and nucleolin (NCL) are under intense investigation, based on their overexpression at the surface of cancer cells." (PMID 28542563, 2017). "The expression of SST, SSTR2, SSTR3 and SSTR5 mRNA in the normal and cancer groups was detected using RT-PCR." (PMID 24260078, 2013). "In order to reduce the rate of clearance of the tracer in the blood, we also added Phe to increase the lipid solubility of the ligand, and finally designed and synthesized a double-specific dimer radiotracer targeting SSTR2 and FAP for cancer imaging and even future therapeutic studies." (PMID 39770488, 2024). "This expression in SSTR2-positive cancer tissues was 8 to 10 times higher than in non-cancerous pancreatic tissue." (PMID 38791582, 2024). "Another study found that the antiproliferative effects of SSTR2 were both cytostatic (growth suppression) and cytotoxic (apoptosis) by affecting the cellular apoptotic level, MAPK, and angiogenic signaling molecules in SSTR2-positive and -negative cancers." (PMID 37900156, 2023). "Additional IHC markers of NET differentiation include somatostatin receptor type 2 (SSTR2), which can also be used to infer somatostatin analogue (SSA) sensitivity and utility of SSTR functional imaging and is reduced in poorly differentiated cancers." (PMID 36826704, 2023). "Furthermore SSTR3, -4 and -5; SSTR3 and -5; and SSTR2, -3 and -5 are also expressed in HT-29, Caco-2 and HCT119 cancer cells, respectively." (PMID 38203605, 2023). "The NET cell lines with low (BON-1) or relatively high (NCI-H727) SSTR2-expression levels, and non-NET cancer and normal cells were treated with chemotherapeutic drugs and assessed for upregulation of SSTR2." (PMID 33435224, 2021). "The very high level of SSTR2 expression in neuroendocrine tumours would not prevent this approach of being in these rare cancers." (PMID 34439195, 2021). "SSTR2 has been shown to bind directly to the p85 subunit of PI3K, which belongs to the class IA PI3Ks and is the class specifically involved in promoting cell survival, growth and proliferation and the most important subclass involved in human cancers." (PMID 29973528, 2018). "While SSTR2 is a classical cell surface receptor, NCL was discovered by chance, tracing back to the identification of a G-quadruplex forming aptamer, later on referred to as AS1411, with anti-cancer activity." (PMID 28542563, 2017). "In contrast, somatostatin receptor 2 expression levels were not sufficiently high in H1299 cells to confer efficient uptake by either non-cancer stem cells or cancer stem cells." (PMID 28542563, 2017). "Both SSTR2 and NCL have previously been reported to be overexpressed by cancer cells." (PMID 28542563, 2017). "SSTR2 was higher expressed in all cancer cell lines versus the normal cell lines up to about 10,000-fold." (PMID 28542563, 2017). "Nucleolin is expressed highly but not selectively, while somatostatin receptor 2 is expressed selectively but not highly by cancer cells." (PMID 28542563, 2017).
cancer (continued). "The rate of positive SSTR-2 mRNA expression among carcinous tissue, adjacent tissue of cancer, and non-carcinous pancreatic tissues were significantly different via analysis (P < 0.01)." (PMID 25890201, 2015). "In order to evaluate if SSTR2 and NCL can potentially be used for therapeutic delivery in NSCLC cells, we initially determined the relative mRNA expression levels by real-time PCR in the two NSCLC cell lines A549 and H1299 and in a panel of other cancer cell lines." (PMID 28542563, 2017). "SSTR2-negative cancers were more likely to develop metastases over time (p<0.05)." (PMID 25010045, 2014). "Cholecystokinin-2 (CCK-2) receptors represent an important molecular target overexpressed on a range of cancers, and particularly neuroendocrine tumor (NET) with low or absent somatostatin receptor subclass-2 (SSTR-2) expression." (PMID 31659509, 2019). "Even if it is ultimately confirmed that SSTR2 is not among the specific markers of NEPC, the design concept of T-SMPDC and its modular synthesis presented in this work can be readily adapted to accommodate the rapid advances in the field of cancer innervation." (PMID 36839802, 2023). "However, not all carcinomas and TNETs that expressed SSTR2 in our and other studies were EBV-related and therefore other pathways for expression of SSTR2 must exist in these tumors." (PMID 35198446, 2022).
infection (8 papers, 2013 to 2026). The state of being infected such as from the introduction of a foreign agent such as serum, vaccine, antigenic substance or organism. "In endemic regions NPC is associated with infection by Epstein–Barr virus (EBV) which was shown to upregulate the somatostatin receptor 2 (SSTR2) cell surface receptor." (PMID 34638429, 2021). "Real-time PCR analysis indicated that in the inflamed jejunum, a significant increase in SSTR1 and SSTR2 expression was observed on day 14 post-infection." (PMID 29522573, 2018). "The investigators found a significant increase in the SSTR2 expression in the inflamed jejunum following infection, indicating that SSTRs may regulate inflammatory pathways in rat intestine." (PMID 30609928, 2019). "The quantitative PCR results demonstrated that on day 14 post-infection, SSTR1, SSTR2 and SSTR3 mRNA comprised approximately 85%, 12.5%, and 2.5% of SSTR subtypes, respectively in the unweaned rat model." (PMID 29522573, 2018). "Octreotide therapy down-regulated the expression of SSTR2 on day 37 post-infection but significantly increased expression of SSTR1, SSTR2 and SSTR3 on day 50 post-infection." (PMID 29522573, 2018). "The levels of jejunal SSTR1, SSTR2 and SSTR3 mRNA transcripts increased by more than 98% from day 14 to day 37 post-infection." (PMID 29522573, 2018). "The data indicated that on day 14 post-infection, SSTR1 and SSTR2 mRNA levels were significantly increased." (PMID 29522573, 2018). "On day 50 post-infection, previously infected, octreotide-treated animals exhibited significantly elevated levels of SSTR1, SSTR2 and SSTR3 mRNA compared with previously infected, untreated rats (p<0.05 and p<0.01, respectively)." (PMID 29522573, 2018). "The present study demonstrated that octreotide therapy, administered at 50 μg/kg/day by intraperitoneal injection from day 10 to 17 post-infection, decreased mRNA levels of SSTR1 and SSTR2 on day 14 post-infection, although it increased mRNA levels of SSTR1, SSTR2 and SSTR3 on day 50 post-infection." (PMID 29522573, 2018). "Our experiments revealed that the SSTR2 expression was enhanced under these inflammatory and microbial conditions, indicating that the SST/SSTR system might play an important role in periodontal inflammation and infection." (PMID 30609928, 2019). "Although SSTR1 and SSTR2 expression levels were increased following infection, SSTR3 mRNA was not significantly modified on days 14, 37 and 50 post-infection." (PMID 29522573, 2018). "Following the period of intestinal parasite clearance, by day 14 post-infection, the mRNA levels of SSTR1, SSTR2, but not SSTR3 were significantly higher in the tissues extracted from the jejunum of C. parvum-infected animals compared with those of the control animals (p<0.05)." (PMID 29522573, 2018).
liver (5 papers, 2019 to 2025). "To address the assumption that SSTR2 correlates among a patient’s lesions, we identified paired samples from primary tumor, lymph node and liver metastases from 34 patients represented on the TMA." (PMID 33922482, 2021). "It has been found that octreotide can stimulate NHE8 expression in colonitis mice, and somatostatin receptor 2 (SSTR2) agonist fragments and somatostatin receptor 5 (SSTR5) agonists can inhibit ERK1 / 2 phosphorylation by restoring NHE8 expression." (PMID 31139644, 2019). "We measured the distribution of 64Cu-labeled SARTATE in a metastatic model of NB, demonstrated its localization in liver metastases using PET (64Cu) and SPECT (67Cu), and confirmed the uptake of [64Cu]Cu-SARTATE in viable, SSTR2-expressing regions of the liver metastases." (PMID 33630166, 2021).
adenocarcinoma (3 papers, 2009 to 2025). A common cancer characterized by the presence of malignant glandular cells. "Intermediate-grade adenocarcinomas zones, represented by Gleason grade 3, showed low SSTR2 expression (“+”) in 11/13 cases or lightly reduced expression (“++”) in 2/13 cases." (PMID 19365586, 2009). "However, low-grade adenocarcinomas zones, represented by Gleason grade 1 or 2, showed lightly reduced SSTR2 expression (“++”) in 6/12 cases or were normal." (PMID 19365586, 2009). "High-grade adenocarcinomas zones, represented by Gleason grade 4 or 5, were negative in 1/20 case, showed low SSTR2 expression (“+”) in 15/20 cases or lightly reduced expression (“++”) in 4 cases." (PMID 19365586, 2009).
CNS tumor (2 papers, 2025). "While DOTATATE-based radiotracers targeting SSTR2 have shown promise in NB management, recent evidence highlights SSTR2A expression in several pediatric CNS tumors." (PMID 40563556, 2025). "68Ga-DOTANOC (68Ga-DOTA-NaI3-Octreotide), a PET tracer with broader affinity for SSTR2, SSTR3, and SSTR5, has been evaluated in pediatric CNS tumors." (PMID 40563556, 2025).
SSTR2 also shares sentences with these, for which no sentence is quoted: somatotroph adenomas (7 papers); metastatic cancers (3); type 2 diabetes mellitus (3); colon carcinoma (2); gastrinomas (2); laryngeal squamous cell carcinoma (2); Merkel cell carcinoma (2); non-functioning pituitary adenoma (2); non-Hodgkin lymphoma (2); acoustic neuroma (1); acute myocarditis (1); adenosquamous carcinoma (1); Adrenal insufficiency (1); Alpha-thalassemia (1); Atypical Meningioma (1); benign meningioma (1); carcinoid tumours (1); cardiac sarcoidosis (1); cervical cancer (1); chronic obstructive pulmonary disease (1); colonitis (1); coronary atherosclerosis (1); diffuse astrocytoma (1); endolymphatic sac tumor (1); endometrial cancer (1); exocrine pancreatic tumour (1); follicular dendritic cell sarcoma (1); germ cell tumor (1); gonadotroph adenomas (1); gynecologic cancers (1).
A further 52 diseases each share a sentence with SSTR2 in 1 paper.